RNU2-57P (RNA, U2 small nuclear 57, pseudogene)
Gene: Small nuclear RNA gene on chromosome Y (5,019,076 to 5,019,266, forward strand). Ensembl gene ENSG00000252468.
Homologues: Orthologues: chimpanzee U2 (99% identical), macaque U2 (87% identical), mouse Gm26020 (76% identical), rat LOC120099513 (76% identical), guinea pig U2 (75% identical). Paralogues in human: RNU2-26P (99% identical), U2 (90% identical), U2 (87% identical), RNU2-6P (86% identical), RNU2-4P (85% identical), RNU2-2 (84% identical), RNU2-59P (84% identical), RNU2-36P (83% identical), RNU2-64P (83% identical), RNU2-3P (82% identical), RNU2-48P (82% identical), RNU2-61P (82% identical), and 67 more.